TP73 (tumor protein p73)
Description:
Participates in the apoptotic response to DNA damage. May be a tumor suppressor protein. Is an activator of FOXJ1 expression (By similarity). It is an essential factor for the positive regulation of lung ciliated cell differentiation.
Synonyms: P73; CILD47
Tractability: Antibody: its Gene Ontology location is reachable by antibodies, with high confidence; the Human Protein Atlas places it where antibodies can reach. PROTAC: UniProt records ubiquitination sites on it; ubiquitination databases record sites on it.
Gene: Protein-coding gene on chromosome 1 (3,652,516 to 3,736,201, forward strand). Ensembl gene ENSG00000078900.
Subcellular location: Nucleus; Cytoplasm
Subcellular location (Human Protein Atlas): Nucleoplasm; Basal body; Cell Junctions; Centrosome; Golgi apparatus; Plasma membrane; Vesicles
Pathways (Reactome):
Gene expression (Transcription): RUNX1 regulates transcription of genes involved in differentiation of HSCs
Programmed Cell Death: Activation of PUMA and translocation to mitochondria
Gene Ontology:
Molecular function: DNA-binding transcription activator activity, RNA polymerase II-specific; DNA-binding transcription factor activity; DNA-binding transcription factor activity, RNA polymerase II-specific; DNA-binding transcription factor binding; identical protein binding; MDM2/MDM4 family protein binding; protein binding; protein kinase binding; RNA polymerase II cis-regulatory region sequence-specific DNA binding; RNA polymerase II-specific DNA-binding transcription factor binding; transcription cis-regulatory region binding; promoter-specific chromatin binding; DNA binding
Biological process: DNA damage response; negative regulation of cardiac muscle cell proliferation; positive regulation of DNA-templated transcription; positive regulation of lung ciliated cell differentiation; positive regulation of transcription by RNA polymerase II; regulation of cell cycle; regulation of gene expression; regulation of mitotic cell cycle; intrinsic apoptotic signaling pathway in response to DNA damage; mismatch repair; positive regulation of apoptotic signaling pathway; regulation of apoptotic process; apoptotic process; positive regulation of cell differentiation; protein tetramerization; regulation of DNA-templated transcription
Cellular component: nucleoplasm; nucleus; transcription regulator complex; chromatin; cytosol; cytoplasm
Genetic constraint (gnomAD): Loss-of-function variants: 24 observed, 58.57 expected, observed/expected ratio (o/e) 0.41, 90% interval 0.3 to 0.58. The upper end of that interval is the gene's LOEUF score, 0.58, which puts it in group 2 of 6, group 1 being the genes least tolerant of losing a copy. Missense variants: 744 observed, 878.25 expected, observed/expected ratio (o/e) 0.85, 90% interval 0.8 to 0.9. Synonymous variants: 416 observed, 370.18 expected, observed/expected ratio (o/e) 1.12, 90% interval 1.04 to 1.22.
Gene-disease validity (ClinGen):
ClinGen rates the evidence that TP73 causes each of these diseases.
ciliary dyskinesia, primary, 47, and lissencephaly (autosomal recessive): Strong.
Homologues: Orthologues: chimpanzee TP73 (99% identical), macaque TP73 (98% identical), rat Tp73 (90% identical), pig TP73 (89% identical), guinea pig TP73 (89% identical), mouse Trp73 (84% identical), tropical clawed frog tp73 (79% identical), zebrafish tp73 (72% identical). Paralogues in human: TP63 (57% identical).
Diseases named in the same sentence as TP73 in open-access papers:
TP73 is named in the same sentence as 129 diseases in open-access papers, as found by Europe PMC text mining. Sharing a sentence is not in itself a finding about the gene and the disease. The quoted sentences say what the papers report.
breast carcinoma (22 papers, 2011 to 2024). "In summary, our works demonstrate that 4 autophagy-related mRNA (APOL1, HSPA8, SIRT1, and TP73) are significantly associated with the early relapse of breast cancer during the postoperative follow-up." (PMID 35250881, 2022). "Similarly, mutations are uncommon in TP73 but it is overexpressed in high grade breast cancers." (PMID 30018742, 2018). "The authors robustly support the opposite functions of both TP73 variants in angiogenesis in a HIF1‐α dependent manner and identified angiogenesis and hypoxia signatures in breast cancer patients with high ΔNp73 levels." (PMID 35586989, 2022). "Survey of the cancer genome atlas (TCGA) revealed hypermethylation across the entire TP73 gene in breast cancers, as compared to normal breast tissues, that varied by estrogen receptor (ER) status and intrinsic mRNA (PAM50) subtypes." (PMID 32825620, 2020). "In breast cancer, high TP73 expression was connected to more metastatic lymph nodes, vascular invasion, and advanced pathological stage." (PMID 31332036, 2019). "We find that high expression of BATF (P = 0.0035) and TP73 (P = 0.0077) is correlated with breast cancer patient survival in HER2+ and Basal-like subtypes, respectively." (PMID 28957321, 2017). "In fact, it has been shown that both MMP23B and TP73 are affected by hypermethylation of CpG sites in their promoter region, a mechanism that may activate breast cancer tumorigenesis." (PMID 33684137, 2021). "Furthermore, TP73 overexpression has been reported in several tumor types, including breast cancer, melanoma, prostate cancer and neuroblastoma, and was shown to induce metastasis, chemo-resistance and other hallmarks of tumor progression that confer poor clinical outcome." (PMID 34692159, 2020). "Among the genes regulated by Bcl-2 in both melanoma and breast carcinoma models we identified CTGF, CCND3, TEAD2, FST, MYC and TP73." (PMID 38755629, 2024). "TP73 plays a role in the progression of melanoma, and breast carcinoma, and in YAP-mediated response of breast cancer to therapy." (PMID 38755629, 2024). "NAV3 is a microtubule-binding protein whose expression is regulated by TP73 and induced by EGF in breast cancer cells." (PMID 34298611, 2021). "For example, PVT1 acts as a competitive endogenous RNA that forms a tight network with protein-coding mRNAs, such as CDH1, TP73, TP31, RUNX1, and RUNX via microRNA-200, thereby regulating breast cancer progression." (PMID 32992461, 2020). "Methylation-sensitive high-resolution melting was used to screen promoter methylation in a panel of 13 genes reported as methylated in breast cancer (RASSF1A, TWIST1, APC, WIF1, MGMT, MAL, CDH13, RARβ, BRCA1, CDH1, CDKN2A, TP73, and GSTP1) in 29 tumour pairs (16 ipsilateral and 13 contralateral)." (PMID 26452468, 2015).
neuroblastoma (18 papers, 2007 to 2024). Neuroblastoma (NB) is the most common solid, extracranial childhood tumor. "The association of TP73 expression with clinical outcome in neuroblastoma, the most common malignant solid tumor of childhood, prompted our analysis of the relationship between TP73 RNA and survival in medulloblastoma patients." (PMID 17626635, 2007). "This might be related to promotor methylation or a loss of the genomic locus of TP73 on chromosome 1p.36, which is frequently deleted e.g., in neuroblastomas." (PMID 33168930, 2021). "TP73 maps to chromosome 1p36, a region that is frequently deleted in neuroblastoma (but which remains intact in Kelly cells)." (PMID 38413795, 2024). "We next focused on 1p-intact neuroblastomas and studied the mutational spectrum of neuroblastoma candidate genes (particularly chromosome 1 genes CASZ1, CHD5, PTPN14, KIF1Bβ, NTRK1, and TP73), and their association with clinical prognostic variables." (PMID 35768791, 2022). "The p73 protein was discovered in 1997 as a product of the TP73 gene situated in the region 1p36.33 that is often deleted in neuroblastoma and various other human tumors." (PMID 34207603, 2021). "Silencing of ITCHin vitro stabilizes TP73 protein on neuroblastoma cells and sensitizes the cells to irradiation treatment." (PMID 31974512, 2020). "TP73 was first reported as a candidate suppressor gene localized at chromosome 1p36.3 in neuroblastoma." (PMID 30212456, 2018). "We did not observe any copy number alterations of these two chromosomes in the murine tumors but did find a Tp73 mutation in one of the MYCN driven tumors, this gene is located at the human 1p36 region that is frequently deleted in high-risk neuroblastoma." (PMID 29492199, 2018). "Several of the investigated TSGs have chromosomal locations that are recurrently lost in neuroblastoma: TP73 on 1p, BLU, RARB and RASSF1A on 3p, and PTEN on 10q." (PMID 22984959, 2012). "Surveys have demonstrated overexpression of TP73 RNA in malignancies including colon and hepatocellular carcinoma, and neuroblastoma." (PMID 17626635, 2007). "We identified differential methylation of genes that have been related to cancers such as lymphoma (WNT6, TP73, and CD37), leukaemia (MEIS1, HOXA4, and HOXA5) or neuroblastoma (TP73), as well as genes related to cardiovascular diseases (UCN, PRDM16, TCAP, ALOX5)." (PMID 35354948, 2022). "Transfection of these cell lines with ITCH siRNA could effectively silence the ITCH expression, and result in the stabilization of TP73 protein, which mediated the apoptosis of the neuroblastoma cells upon irradiation treatment." (PMID 31974512, 2020).
cervical carcinoma (11 papers, 2007 to 2025). A carcinoma arising from either the exocervical squamous epithelium or the endocervical glandular epithelium. "We further evaluated the association between TP73 expression and overall survival of cervical cancer patients for investigating the prognostic significance of TP73." (PMID 31332036, 2019). "TP73 expression is up-regulated in cervical cancer tissues, and negatively associated with clinical progression in cervical cancer patients." (PMID 31332036, 2019). "In recent years, G4C14-A4T14 polymorphism of TP73 was identified implicated in the tumorigenesis of a variety of cancer types, including breast cancer, colorectal cancer, lung cancer, cervical cancer, esophageal cancer and so on." (PMID 30420492, 2018). "Besides, DNA methylation and genetic mutations were found in TP73 gene during cervical cancer carcinogenesis." (PMID 31332036, 2019). "All in all, our recent updated meta-analysis draws a comprehensive, precise and convincible result, which is that G4C14-A4T14 polymorphism of TP73 is strongly associated with the increasing cancer risk, especially for Caucasian, cervical cancer and colorectal cancer." (PMID 30420492, 2018). "However, we further evaluated the association between TP73 expression and overall survival of cervical cancer patients in TCGA database, and found that TP73 expression was positively correlated with overall survival time in cervical cancer patients." (PMID 31332036, 2019). "Thus, we further analyzed the clinical significance of TP73 expression in cervical cancer patients, and found high expression of TP73 was markedly associated with early clinical stage, less lymph node metastasis, absent distant metastasis, squamous cell carcinoma and favorable histological grade." (PMID 31332036, 2019). "Further research should focus on understanding the molecular mechanisms underlying the relationships between EPGN, LCN10, TP73, and ICI therapy, and explore their therapeutic potential in cervical cancer treatment." (PMID 38933923, 2024). "For instance, decreased expression of NUSAP1 and TP73 predicts poor overall survival in cervical cancer." (PMID 35832191, 2022). "TP73 was also reported to act as a credible biomarker for predicting favorable OS in cervical cancer patients." (PMID 34790823, 2021). "High TP73 expression is an independent factor for predicting favorable overall survival in cervical cancer." (PMID 31332036, 2019). "In the results, we found cervical cancer tissues exhibited high TP73 expression in comparison with normal cervical epithelium tissues, which was consistent with the expression status of TP73 in The Cancer Genome Atlas (TCGA) database." (PMID 31332036, 2019). "In our study, we found that cervical cancer tissues exhibited high TP73 expression in comparison with normal cervical epithelium tissues, which was consistent with the expression status of TP73 in TCGA database." (PMID 31332036, 2019). "In our study, TP73 protein expression was detected by immunochemistry in 118 paraffin-embedded cervical cancer tissue specimens and 40 paraffin-embedded normal cervical epithelium tissue specimens." (PMID 31332036, 2019). "The correlations between TP73 expression and clinicopathological features in cervical cancer were further estimated to explore the clinical significance of TP73." (PMID 31332036, 2019). "While in the cervical cancer tissues, high-expression of TP73 was observed in 12.5% (5/40) tumor samples." (PMID 31332036, 2019). "In conclusion, TP73 expression is increased in cervical cancer tissues and cells, and acts as a credible biomarker for predicting favorable overall survival in cervical cancer patients." (PMID 31332036, 2019).
cervical carcinoma (continued). "Afterward, TP73 was suggested to be overexpressed in cervical cancer tissues compared with normal cervical tissues." (PMID 31332036, 2019). "Yet, due to the limited sample size of patients in these two studies, further research is still needed to confirm these findings and establish the clinical value of TP73 expression as a reliable prognostic predictor for the outcome of cervical cancer patients." (PMID 31332036, 2019). "The overall survival curve of our study also showed cervical cancer patients with high expression of TP73 had better clinical outcome than those with low expression of TP73 (P<0.001)." (PMID 31332036, 2019). "Generally, high TP73 expression is a credible biomarker for predicting favorable prognosis in cervical cancer patients." (PMID 31332036, 2019). "In order to explore the expression status of TP73 in cervical cancer, we first observed TP73 expression in cervical cancer tissues and normal cervical epithelium tissues using the TCGA database." (PMID 31332036, 2019). "The Kaplan–Meier method and log-rank test were performed based on the expression level of TP73 in a cervical cancer cohort from the TCGA database, and showed that TP73 expression was positively correlated with overall survival time in cervical cancer patients." (PMID 31332036, 2019). "In cervical cancer, TP73 staining was originally observed in the basal and parabasal layers of cervical epithelium, high-grade intraepithelial neoplasia and squamous cell carcinoma." (PMID 31332036, 2019). "In the TCGA database, the TP73 expression was obviously up-regulated in cervical cancer tissues compared with normal cervical epithelium tissues (P<0.001)." (PMID 31332036, 2019). "Since immunohistochemistry is the most common method in pathologic diagnosis and clinical practice, we conducted immunohistochemical staining to detect TP73 expression, and analyzed the clinical and prognostic values of TP73 in cervical cancer." (PMID 31332036, 2019). "In silico analysis revealed that the expression of TP73 in cervical cancer tissue is higher than it in corresponding normal tissue, as well as in cervical cancer." (PMID 30420492, 2018). "Moreover, we further performed immunohistochemical analysis to assess TP73 protein expression in cervical cancer tissues and normal cervical epithelium tissues." (PMID 31332036, 2019). "Due to lack of reports about the correlation between TP73 protein expression and clinicopathologic features of cervical cancer, the aim of our research was to explore the clinical and prognostic significance of TP73 protein expression in cervical cancer patients." (PMID 31332036, 2019). "Furthermore, the overall survival curve of our study also showed cervical cancer patients with high expression of TP73 had better clinical outcome than those with low expression of TP73." (PMID 31332036, 2019). "Furthermore, the result of multivariate Cox proportional hazards regression model suggested that high TP73 expression was an independent factor for predicting unfavorable overall survival in cervical cancer patients (P=0.039)." (PMID 31332036, 2019). "Furthermore, high TP73 expression was identified as an independent factor for predicting favorable overall survival in cervical cancer patients through univariate and multivariate Cox proportional hazards regression model." (PMID 31332036, 2019). "Moreover, univariate and multivariate Cox proportional hazards regression model indicated that high TP73 expression was identified as an independent factor for predicting favorable overall survival in cervical cancer patients." (PMID 31332036, 2019). "First, the Kaplan–Meier method and log-rank test were performed based on expression level of TP73 in cervical cancer cohort from the TCGA database, and showed that TP73 expression was positively correlated with overall survival time in cervical cancer patients (P=0.009)." (PMID 31332036, 2019).